IGF1 (insulin like growth factor 1)
Diseases named in the same sentence as IGF1 in open-access papers (continued):
Sharing a sentence is not in itself a finding about the gene and the disease.
metabolic syndrome (continued). "Consequently, we have identified FLT1, SPP1, CD44, and IGF1 as the critical genes shared among the clusters in the PPI network of AD and metabolic syndrome." (PMID 38809924, 2024). "So, presence of higher IGF-1 in our patient did not influence increase numbers of metabolic syndrome components." (PMID 37497348, 2023). "In addition, adiponectin and insulin-like growth factor-1 (IGF-1) were both seen to be upregulated by calcitriol, both of which are protective against inflammation and metabolic syndrome, respectively." (PMID 34836382, 2021). "Also developing a new prevention and treatment strategies for increasing serum IGF-1 levels would benefit in controling low HDL-C and metabolic syndrome." (PMID 27343122, 2016). "In Chinese nondiabetic obese children and adolescents, we observed that the association between low IGF-1 SDS and metabolic syndrome was independent of age, gender and pubertal status." (PMID 27343122, 2016). "OB patients displayed no metabolic syndrome, but their IGF-1 was significantly decreased compared to controls (p = 0.02)." (PMID 27611669, 2016). "Several studies had suggested that IGF-1 had robust negative relationships with metabolic syndrome and its components." (PMID 27343122, 2016). "In the overall study populations, patients with metabolic syndrome showed significant increase in the IGFBP-7/IGF-1 ratio compared to patients without metabolic syndrome (0.53 [0.41-0.74] vs. 0.47 [0.36-0.59], respectively, p =0.002)." (PMID 27769173, 2016). "Normalization of serum GH and IGF1 levels has been shown to improve clinical and metabolic abnormalities in acromegalic patients, especially cardiomyopathy, OSA, arterial hypertension and dyslipidemia." (PMID 26429918, 2015). "The impact of GH/IGF-1 discrepancy on dyslipidemia has not been explored yet." (PMID 37829686, 2023). "Therefore, in this present study, we aimed to investigate the association between IGF-1 and HDL-C, metabolic syndrome in nondiabetic obese children and adolescents." (PMID 27343122, 2016). "Although some evidence has been provided that low serum 25-hydroxyvitamin D (25-OH-D) may be involved in the development of the metabolic syndrome, one has to be aware of several possible confounders like PTH, serum calcium, factors involved in the IGF1 system, physical activity, and social status." (PMID 24026893, 2013). "The aim of this study is to investigate the relationship among IGF-1, HDL-C and the metabolic syndrome in Chinese nondiabetic obese children and adolescents." (PMID 27343122, 2016).
colorectal cancer (181 papers, 1990 to 2026). A primary or metastatic malignant neoplasm that affects the colon or rectum. "Elevated circulating IGF-1 levels have been positively associated with increased risk of breast, prostate, and colorectal cancers." (PMID 41262902, 2025). "High circulating IGF-1 levels are associated with prostate and breast cancer, and some studies suggest associations with colorectal cancer." (PMID 39200386, 2024). "Previous reports found that high IGF1 level was associated with an increased risk of lung, prostate, breast, and colorectal cancers." (PMID 36774408, 2023). "A series of studies have shown that high levels of IGF‐1 are associated with an increased risk of tumors including prostate, pre‐ and postmenopausal breast, lung, thyroid, and colorectal cancers." (PMID 35048526, 2022). "IGF-1 is a bioactive protein polypeptide, and it has been previously reported that serum IGF-1 levels are associated with prostate, breast, pancreatic, lung, and colorectal cancer." (PMID 36389727, 2022). "Estrogenic compounds reduce the concentration of serum insulin-like growth factor-l (IGF-1), a mitogen associated with the increased risk of colorectal cancer." (PMID 36389202, 2022). "An increase in serum IGF‐1 level of 100 ng/ml was shown to correspond to a 69% increase in colorectal cancer risk." (PMID 35048526, 2022). "Paracrine IGF1/IGF1R signaling initiated by radiotherapy-activated cancer-associated fibroblasts promotes colorectal cancer progression, and the radiation-induced secretion of IGF1 in human fibroblasts up-regulated IGF1R/Akt signaling in bystander cells." (PMID 34178997, 2021). "In analysis using the SNP in the IGF1 gene as instrument, a suggestive association between genetically predicted IGF‐1 levels and colorectal cancer was observed (OR 1.74; 95% CI 1.02‐2.97; P = .04)." (PMID 32717139, 2020). "This study found some support for a causal association between elevated serum IGF‐1 levels and increased risk of colorectal cancer." (PMID 32717139, 2020). "In conclusion, these MR findings support a potential causal association between increased serum IGF‐1 levels and higher risk of colorectal cancer." (PMID 32717139, 2020). "There was a suggestive positive association of genetically predicted serum IGF‐1 levels with colorectal cancer." (PMID 32717139, 2020). "Possible mechanisms underlying the increased colorectal cancer risk include direct actions of IGF‐1 on cell growth or indirect effects via for example insulin resistance and elevated insulin levels." (PMID 32717139, 2020). "It is now well-established that subjects in the general population who have serum IGF-1 levels at the upper end of the normal range are at increased risk of developing several types of cancer including prostate, breast and colorectal cancer." (PMID 31416218, 2019). "High circulating IGF1 has also been linked to more locally advanced stages of colorectal cancer and less differentiated cases of colorectal cancer." (PMID 28966806, 2017). "The same positive association was observed between circulating IGF-1 level and a risk for breast and colorectal cancer." (PMID 23530598, 2013). "The association of the CA repeat polymorphism in the promoter region of the IGF-1 with circulating IGF-1 levels and a risk of breast, prostate, and colorectal cancers have been extensively evaluated." (PMID 23530598, 2013). "Great attention had been provided to colorectal cancer since a high level of IGF1 has been correlated to increase risk of colorectal cancer." (PMID 22891085, 2012). "In a previous study conducted within the Women's Health Initiative Observational Study, we showed that serum insulin, waist circumference, and free IGF-1 were each positively associated with colorectal cancer incidence in multivariate models." (PMID 22127286, 2012).
colorectal cancer (continued). "It is also unlikely that IGF-1 plays a role in the link between OC use and colorectal cancer risk as we would anticipate lower IGF-1 levels in past users who have a lower risk of colorectal cancer." (PMID 21599947, 2011). "Both IGF-1 and OC use have been linked to premenopausal breast and colorectal cancers, osteoporosis and cardiovascular disease (CVD)." (PMID 21599947, 2011). "GH, IGF-1 and insulin have cancer-promoting actions and raised serum IGF-1 levels have been associated with increased risk of prostate, breast and colorectal cancers." (PMID 21699736, 2011). "Of note, in the large EPIC cohort with 1,121 colorectal cancer cases, moderate positive associations between IGF-1 levels and risk was observed only in those with low milk (and hence calcium) intakes." (PMID 22216097, 2011). "have reported that IGF1 was associated with the pivotal precursor to colorectal cancer." (PMID 36518255, 2022). "The possible mechanisms explaining the increased colorectal cancer risk might be a direct effect of IGF1 on cell growth or an indirect effect, such as insulin resistance and raised insulin levels." (PMID 34858769, 2021). "Further research is recommended to investigate if circulating IGF1 and IGFBP3 levels can be used to identify people at high risk of colorectal cancer and to investigate potential lifestyle or pharmaceutical ways to lower IGF1 bioactivity as a risk reduction strategy." (PMID 34858769, 2021). "Circulating IGF1 level plays a significant role as a risk factor for the onset and development of various tumors by the increase of neoplastic cell proliferation, such as lung, breast, ovarian and colorectal cancers." (PMID 34178997, 2021). "Moreover, the association between genetically predicted IGF‐1 levels and colorectal cancer was replicated in an independent cohort of Japanese individuals." (PMID 32717139, 2020). "Genetically predicted serum IGF‐1 levels were associated with colorectal cancer." (PMID 32717139, 2020). "Therefore, further research is required to investigate the role of obesity, ethnicity, and dietary habits possibly as confounders to IGF‐1 and colorectal cancer risk." (PMID 27734632, 2016). "Other lifestyle risk factors for colorectal cancer, such as increased caloric intake, being overweight, and having a sedentary lifestyle, have demonstrated higher levels of IGF-1 via increased insulin production and subsequent inhibition of IGF-binding protein synthesis." (PMID 27598322, 2016). "If high IGF-1 and high insulin underlie in part the high risk of colorectal cancer in Western countries, our findings suggest that vitamin D status may be one particularly important factor in such populations." (PMID 22216097, 2011). "The results from this study suggest that improving vitamin D status may help lower risk of colorectal cancer associated with higher IGF-1/IGFBP-3 ratio or C-peptide levels." (PMID 22216097, 2011). "In conclusion, if confirmed in other studies, the results from this study suggest that improving vitamin D status may help lower risk of colorectal cancer associated with higher IGF-1/IGFBP3 ratio or C-peptide levels." (PMID 22216097, 2011). "IGF-1 is positively associated with breast and colorectal cancers in some studies." (PMID 21599947, 2011). "Therefore, it is possible that high IGF-1 may be one of the underlying biological mechanisms mediating the association of height and colorectal cancer." (PMID 27598322, 2016). "However, from a public health point of view, if confirmed these findings would provide a relatively easy way to reduce risk of colorectal cancer among those with high IGF-1/IGFBP-3 ratio or high C-peptide levels as vitamin D status is an easily modifiable risk factor." (PMID 22216097, 2011).
colorectal cancer (continued). "High insulin levels stimulate the production of IGF-1 by liver cells after insulin binds to its receptor, whereas IGF-1 can also bind to insulin-like growth factor binding protein 3 (IGFBP-3), which is associated with a greater risk of colorectal cancer." (PMID 40457130, 2025). "The authors observed increased expression of IL-10 and IL-13 and decreased expression of IL-1β, IL-6, interferon gamma (IFN-γ), TNF-α, IL-12, and IGF-1 in peripheral blood mononuclear cells (PBMCs) derived from patients with colorectal cancer." (PMID 38957737, 2024). "IGF-1 can promote colorectal cancer metastasis by mediating HOXA13 overexpression, and IGF-1 promotes gastric cancer growth and metastasis by inducing IFITM2." (PMID 38342894, 2024). "IGF-1 signaling has been shown to regulate the cancer stemness in various models of SCs, including colorectal cancer SCs." (PMID 36835075, 2023). "For colorectal cancer patients, levels of IGF-1 appeared to decline steadily after surgery and reached minimum concentrations by POD3 before returning to baseline." (PMID 38067195, 2023). "They found that higher levels of IGF-1 and IGFB3 were associated with the risk of colorectal cancer." (PMID 37895144, 2023). "For example, many colorectal cancer patients are considered malnourished before surgery, which has been shown to impair IGF-1 function, leading to chronic inflammation." (PMID 38067195, 2023). "It is suggested that monensin can down-regulate the expression of IGF1R in human colorectal cancer cells, which has a synergistic anti-proliferation effect with overexpression of IGF1." (PMID 36896461, 2023). "The results of a study involving 80 colorectal cancer patients and 80 matched controls revealed that TT and CT genotypes of rs6214C>T had the highest serum IGF1 levels (P= < 0.001)." (PMID 37284192, 2023). "Monensin was shown to target multiple cancer-related signaling pathways such as Elk1, AP1, as well as Myc/max, and suppressed IGF1R expression via increasing IGF1 in colorectal cancer cells." (PMID 36896461, 2023). "Another study highlighted IGF1 as one of the drivers in the transition between adenoma and colorectal cancer, IGF1 was also identified in our study with a decreased expression profile in polyps." (PMID 35486660, 2022). "Current knowledge on the role of miRNAs and lncRNAs on the GH/IGF1 axis and IGF system in colorectal cancer." (PMID 34484116, 2021). "Numerous investigations have demonstrated that the expression level of insulin-like growth factor-1 (IGF-1) and IGF-1 receptor (IGF-1R) in colorectal cancer patients is associated with poor prognosis, chemoresistance, and increased invasiveness features." (PMID 34992527, 2021). "High IGF1 levels and low concentrations of IGFBP3 are related to colorectal cancer and were significantly associated with liver metastasis, lymph node spread, and lymphovenous invasions." (PMID 34858769, 2021). "Diverse in vitro and in vivo studies have shown that insulin and Insulin-like Growth Factor (IGF-1) have mitogenic effects on colorectal cancer cells, stimulating cell proliferation and inhibiting apoptosis." (PMID 33672318, 2021). "The OR of colorectal cancer per SD increase of genetically predicted IGF‐1 levels was 1.22 (95% CI 1.09‐1.36; P = 3.9 × 10−4) when using the full set of SNPs and 1.57 (95% CI 1.02‐2.41; P = .04) when using the SNP in the IGF1 gene." (PMID 32717139, 2020). "IGF-1 prevents autophagy in human colorectal carcinoma cells, but the role of IGF-1 in the regulation of autophagy remains to be elucidated." (PMID 32116650, 2020). "The Insulin-like growth factor-I/Insulin-like growth factor-I receptor (IGF-1/IGF-1R) system is a major determinant in colorectal cancer (CRC) pathogenesis." (PMID 31480481, 2019). "IGF1 increases cell migration and invasion in vitro in a range of cancer cells, including human colorectal carcinoma and human multiple myeloma cells." (PMID 30348128, 2018).
colorectal cancer (continued). "In colorectal cancer, the circulating levels of IGF‐1 is particularly influenced by nutritional status." (PMID 27734632, 2016). "This section summarizes studies on the emerging role of IGF‐1 in the development of SPCs with a focus on the definition of SPC as well as their potential link with IGF‐1 in the case of patients with primary breast, lung, prostate, and colorectal cancer." (PMID 27734632, 2016). "The combination of IGF-1 and extremely low-dose chemotherapy significantly induced cell viability in WiDr colorectal cancer cells." (PMID 24396438, 2014). "IGF-1 has been detected in colorectal cancers and is a strong stimulator of colorectal cancer cell proliferation in vitro, but GH treatment usually results in increases in both IGF-I and IGFBP-3." (PMID 23761782, 2013). "Past studies have shown that amplified insulin-like growth factor 1 (IGF1)/IGF1 receptor (IGF1-R) signalling has an important role in colorectal cancer (CRC) development, progression and resistance to treatment." (PMID 22710713, 2013). "The reduction of the IGF binding protein (IGF1 BP) and increasing IGF1 in low levels of adiponectin concentrations can increase cell proliferation and inhibits apoptosis in colorectal cancer cells." (PMID 23213569, 2012). "Subjects with IGF-1 levels in the highest quintile were more likely to develop colorectal cancer compared with subjects with IGF-1 levels in the lowest quintile." (PMID 23304125, 2012). "The plasma concentrations of IGF-1 and IGF binding protein-3 (IGFBP-3) were reported to influence the risk of colorectal cancer in a prospective cohort of 14,916 men." (PMID 23304125, 2012). "First, the earlier study was a case-cohort study conducted in the WHI OS and had a larger sample size (438 colorectal cancer cases) and measured a number of hormones, including insulin, IGF-1, and estradiol." (PMID 22127286, 2012). "In our study associations between IGF-1, the molar IGF-1/IGFBP-3 ratio and C-peptide and colorectal cancers were similar for men and women." (PMID 22216097, 2011). "This is the first study to investigate the associations of IGF-1, IGF-2 and IGFBP-3 concentrations with the risk of colorectal cancer in prospectively collected blood samples from an Oriental population." (PMID 11742490, 2001). "In colorectal cancer, IGF1 stimulation activates the IGF1R/AKT pathway and induces the transcriptional activation and expression of the transcription factor HOXA13, thereby promoting the in vitro migratory and invasive abilities of colorectal cancer cells and in vivo metastases formation." (PMID 38892104, 2024). "However, this method has various drawbacks, including the need for frequent injections and the positive correlation between IGF-1 blood levels and the incidence of prostate, breast, and colorectal cancers." (PMID 38534273, 2024). "Other effects include m6A modifications, glycolysis-associated lncRNA of colorectal cancer (GLCC1), and insulin-like growth factor 1 (IGF-1) signaling, which could also enhance glycolysis in different paths." (PMID 37182124, 2023). "It suggests that monensin combined with treatment targeting IGF1R or IGF1 may potentiate anti-cancer effect in colorectal cancer, which needs further investigation." (PMID 36896461, 2023). "The biological function of IGF1 signaling has been reported in various types of cancer, including hepatocellular carcinoma, breast cancer, ovarian cancer, prostate cancer, and colorectal cancer." (PMID 36774408, 2023). "The proliferation of colon cancer cells might be significantly promoted by elevated insulin and insulin-like growth factor-1 (IGF-1) levels, then increasing the vitality of transformed cells and ultimately inducing colorectal cancer." (PMID 36553697, 2022).